NCAM1 (neural cell adhesion molecule 1)
Diseases named in the same sentence as NCAM1 in open-access papers (continued):
Sharing a sentence is not in itself a finding about the gene and the disease.
esophageal cancer (4 papers, 2019 to 2022). A primary or metastatic malignant neoplasm involving the esophagus. "With respect to downregulated genes, C16orf89, AR, CKB, ADH1B, and NCAM1 were the leading downregulated genes in patients with esophageal cancer." (PMID 33828156, 2021). "Our analysis showed that following five genes were most significantly downregulated in esophageal cancer: C16orf89 (9.78E−08), AR (1.01E−07), CKB (1.17E−07), ADH1B (1.79E−07), and NCAM1 (2.15E−07)." (PMID 33828156, 2021).
GNE myopathy (4 papers, 2013 to 2022). "Serum GDF15, as well as NCAM1, elevation in GNE myopathy likely results from expression by regenerating muscle fibres during the process of progressive degeneration of the overall tissue." (PMID 35148379, 2022). "NCAM1 in BMD/DMD patients was not significantly different to controls, while in GNE myopathy there was a small increase compared to controls, but still significantly lower than in CMT patients (P = 0.032)." (PMID 35148379, 2022).
nicotine dependence (4 papers, 2012 to 2026). Physical and psychological dependence on nicotine. "NCAM1 encodes neural cell adhesion molecule 1, and was associated with nicotine dependence, alcohol dependence and in multi-trait analyses." (PMID 41044382, 2026).
pituitary adenomas (4 papers, 2017 to 2022). "Druggable genes shared by all types of pituitary adenomas included NRG1, KCNA4, NCAM1, GRIA2 and GRM8." (PMID 33168897, 2020).
prostate tumors (4 papers, 2015 to 2023).
teratoma (4 papers, 2011 to 2026). A non-seminomatous germ cell tumor characterized by the presence of various tissues which correspond to the different germinal layers (endoderm, mesoderm, and ectoderm). "The clinical presentation and paraneoplastic association with teratoma closely resemble anti-NMDAR encephalitis, suggesting that anti-NCAM1 antibodies may define a novel form of AE with psychotic manifestations." (PMID 41694384, 2026).
ZIKV infection (4 papers, 2017 to 2020). "NCAM1 depletion in U-251 MG cells remarkably inhibited ZIKV infection." (PMID 32753727, 2020). "We found that NCAM1 depletion by sgRNA1 in U-251 MG cells remarkably attenuated ZIKV infection." (PMID 32753727, 2020). "Finally, considering NCAM1 was crosslinked at several time points, totally not detected in control samples and NCAM1 is abundantly expressed in brain, we further examined whether NCAM1 is a potential receptor for ZIKV infection leading to neurological disorders." (PMID 32753727, 2020).
atherosclerosis (3 papers, 2022 to 2023). A disease characterized by the build-up of fatty material and calcium deposition in the arterial wall resulting in partial or complete occlusion of the arterial lumen. "Considering the similar pathologic mechanisms between atherosclerosis and CAVD, we conjectured that NCAM1 might also be a new biomarker for aortic valve stenosis." (PMID 35722091, 2022).
Intellectual disability (3 papers, 2021 to 2026). "NCAM1 and ZBTB20 are strong candidates for having a role in cognitive aging with mutations in ZBTB20 resulting in intellectual disability, and NCAM1 previously found to be associated with associative memory in humans." (PMID 34285142, 2021).
ischaemic cardiomyopathy (3 papers, 2013 to 2020). "NCAM1 is involved in cell adhesion, ventricular wall thickness, and cardiomyopathy." (PMID 31825849, 2019).
lung tuberculosis (3 papers, 2019 to 2022). "However, the performance of this modified signature was reduced, compared to what was reported in adults with pulmonary TB, albeit, with transthyretin in place of NCAM1 in the adult study." (PMID 31612118, 2019).
neuropathy (3 papers, 2022 to 2025). A disorder affecting the nervous system that manifests with pain, tingling, numbness, and/or muscle weakness. "GarsC201R and GarsP278KY mice exhibit axon loss and display a behavioural neuropathy phenotype from around 1 month of age, and the elevation of Ncam1 was present at 5 months of age in both mutant models." (PMID 35148379, 2022). "It is also possible that Ncam1 elevation is more associated with axonal phenotypes in mouse model, given that our patients have a relatively advanced neuropathy (CMTES; 14.5 ± 3.3, mean ± SD), while in the C61 het mice the neuropathy starts at 2 months and progresses until 10 months of age." (PMID 35148379, 2022). "Serum NCAM1 concentrations are significantly (P = 0.016) higher in CMT patients with severe neuropathy (CMTES ≥ 10), at 61.3 ng/ml, compared to those with mild neuropathy (CMTES < 10), at 47.6 ng/ml; an increase of 28.7%." (PMID 35148379, 2022). "In Gjb1-null mice, significant elevation of Ncam1 is evident from 6 months, after the onset of the neuropathy which occurs at 3 months of age." (PMID 35148379, 2022). "Our data indicate that serum GDF15 is a highly selective diagnostic biomarker of CMT (AUC of 0.972, 95% CI; 0.936–1), while NCAM1 (AUC 0.748, 95% CI; 0.6268–0.869) is a more suitable serum biomarker of neuropathy progression." (PMID 35148379, 2022). "Furthermore, we have previously shown that both serum Ncam1 levels and clinical symptoms of the neuropathy are restored to wild-type levels following targeted gene therapy in the Gjb1-null mice." (PMID 35148379, 2022). "We believe that NCAM1 has the potential to reflect clinical severity of neuropathy and may respond to treatments, therefore further investigations are recommended in larger cohorts of patients and in clinical trials." (PMID 35148379, 2022). "Together, these data indicate that NCAM1 is increased across different CMT mouse models compared to littermate controls, with the difference becoming more noticeable with increasing age and neuropathy severity." (PMID 35148379, 2022). "NCAM1 as a marker for active neuropathy (although not used in routine clinical practice but for research purposes) was unchanged in serum of our patient." (PMID 40581649, 2025). "We show that NCAM1 may reflect disease severity, demonstrated by a progressive increase in mouse models with time and a significant positive correlation with CMTES neuropathy severity in patients." (PMID 35148379, 2022). "Unlike NCAM1, GDF15 was greatly increased even in mildly affected CMT patients and increased prior to neuropathy onset in the axonal Hsbp8K141N mouse model." (PMID 35148379, 2022).
osteoarthritis (3 papers, 2020 to 2023). A noninflammatory degenerative joint disease occurring chiefly in older persons, characterized by degeneration of the articular cartilage, hypertrophy of bone at the margins and changes in the synovial membrane. "Interestingly, by mining a published microarray database (GSE57218), we found that IFN-related genes (STAT1, IFNGR2, NCAM1, MID1) were highly elevated in the cartilage tissues of osteoarthritis patients." (PMID 32202492, 2020).
primary Sjögren's syndrome (3 papers, 2022 to 2025). "detected an increasing MIP-1b expression of the ocular surface in DED patients, especially in Sjogren syndrome (SS) patients; however, no studies of increasing leptin or NCAM-1 in DED patients have been reported." (PMID 36419616, 2022).
prion disease (3 papers, 2019 to 2025). A transmissible disease that is caused by a protein that is able to induce abnormal folding of normal cellular proteins, leading to characteristic spongiform brain changes, which are associated with neuronal loss without an inflammatory response. "The genes C1QB, C1QC, C7, and NCAM1 were downregulated for Ca and partake in the prion disease pathway." (PMID 31481722, 2019).
Cachexia (2 papers, 2019 to 2020). Severe weight loss, wasting of muscle, loss of appetite, and general debility related to a chronic disease. "Based on the fact that circulating levels of tumor-derived factors were correlated with cachexia development and predicted outcome in cancer, we also investigated the predictive potential of seven transcripts (NCAM1, CNTN1, SCG2, CADM1, IL-8, NPTX1, and APOD)." (PMID 31455042, 2019).
drug dependence (2 papers, 2018 to 2021). "NCAM1 at this locus is involved in development and maintenance of the nervous system and is associated with SCZ and comorbid alcohol and drug dependence." (PMID 34493297, 2021).
experimental autoimmune encephalomyelitis (2 papers, 2020 to 2022). An autoimmune demyelinating disease of the central nervous system that is produced experimentally in animals by the injection of homogenized brain or spinal cord in Freund's adjuvant. "In line with our findings, inflammatory conditions decreased the expression of NCAM1 in the hippocampus and other brain regions of rats exposed to experimental autoimmune encephalomyelitis." (PMID 35634471, 2022).
hemangioblastoma (2 papers, 2016 to 2025). "Hemangioblastomas are usually positive for alpha-inhibin, D2-40, brachyury, NSE, NCAM1, S100, ezrin, CXCR4, aquaporin-1, and occasionally for GFAP and EGFR, and negative for EMA, CD10 and CAM5.2." (PMID 41302074, 2025).
injury (2 papers, 2019 to 2021). Damage inflicted on the body as the direct or indirect result of an external force, with or without disruption of structural continuity. "Neural cell adhesion molecule 1 (NCAM1), which plays a role in neurite outgrowth and spine formation, showed an increased turnover rate after nerve injury in mice." (PMID 34072638, 2021).
leukoplakia (2 papers, 2023 to 2025). A white patch or plaque on a mucous membrane that cannot be characterized clinically or pathologically as any other disease. "NCAM1/CD56 has previously been used by Bondad-Palmario with similar results in oral leukoplakia." (PMID 37190121, 2023).
lung carcinoids (2 papers, 2023 to 2024). "To further ensure consistency of key expression patterns, we compare expression values of four markers of lung carcinoid tumors: NCAM1 (CD35), INSM1, SYP (synaptophysin), and OTP (orthopedia homeobox protein)." (PMID 38706317, 2024).
rectal cancer (2 papers, 2021 to 2025). A primary or metastatic malignant neoplasm that affects the rectum. "According to literature validation, we detected some rectal cancer‐related mRNAs including PRKCB, NCAM1, ZEB1, PCDH7, Cav1 and FGF2 in the subnetwork." (PMID 34613665, 2021).
skin cancer (2 papers, 2020). "NCAM1 facilitates fibroblast growth factor receptor signalling, cell-matrix adhesion, cell migration and subsequently tissue regeneration; however, when up-regulated NCAM1 serves as an immunohistochemical skin cancer marker." (PMID 32900003, 2020).
status epilepticus (2 papers, 2017 to 2022). Status epilepticus is defined as a continuous seizure lasting more than 30 min, or two or more seizures without full recovery of consciousness between any of them. "A very recent study has reported that increased expression of NCAM1 with donepezil (acetylcholinesterase inhibitor) and aniracetam (nootropic) improved spatial memory in status epilepticus rats." (PMID 28253924, 2017).
Ataxia (1 paper, 2021). Ataxia refers to impaired coordination of voluntary muscle movement. "For this purpose, Acp2 (acid phosphatase 2, lysosomal) mutant mice (aka; nax, naked and ataxia) exhibiting excessive PCs migration were examined and the transcription of Ncam1 was evaluated." (PMID 35126044, 2021). "We analyzed the Acp2 mutant mouse (nax: naked and ataxia), which displays excessive PC migration into the molecular layer, and investigated how the excessive migration of PCs along Bergmann glia could correlate to NCAM1 expression pattern in early postnatal days." (PMID 35126044, 2021).
blastoma (1 paper, 2019). A malignant neoplasm composed of undifferentiated cells. "Targeting the progenitor blastoma and these transitions with an anti-NCAM1 immunoconjugate (Lorvotuzumab mertansine) inhibited tumor growth and progression providing new paradigms for PPB therapeutics." (PMID 31477684, 2019).
bone metastasis (1 paper, 2021). Transfer of a neoplasm from its primary site to bones. "Among these genes, NCAM1 expressed higher in bone metastasis group, while CXCL10 and C3 expressed lower in bone metastasis group." (PMID 33859877, 2021).
cardiac conduction disease (1 paper, 2021). "In summary, we have identified and characterized two previously unknown IgSF-CAMs in the VCS and demonstrated that NCAM-1 deficiency leads to defects in PC gene expression, VCS patterning and cardiac conduction disease." (PMID 34100064, 2021). "Mice deficient in NCAM-1, but not CNTN2 or ALCAM, exhibited defects in PC gene expression and VCS patterning, as well as cardiac conduction disease." (PMID 34100064, 2021).
cerebral infarction (1 paper, 2019). An ischemic condition of the brain, producing a persistent focal neurological deficit in the area of distribution of the cerebral arteries. "For example, a previous study showed that the level of NCAM1 was increased in serums of patients with malignant middle cerebral artery infarction (MMI) compared to those with nonacute cerebral infarction (NACI)." (PMID 31781304, 2019).
colitis (1 paper, 2008). Inflammation of the colon. "Thus, TNBS colitis was characterized by an absence of significant changes in markers of T cells (Thy1, Tcrb, Tcrg, Zap70, Lck), B cells (Ptprc -B220-, Ms4a1 -Cd20-, Cd22, Cd79b) and NK cells (Baat, Ncam1 -Cd56-, B3gat1 -Cd57-)." (PMID 18928539, 2008).
gastric ulcer (1 paper, 2014). An ulcerated lesion in the mucosal surface of the stomach. "NCAM1 may also play a role in the healing processes of gastric ulcers." (PMID 24647245, 2014).
generalized anxiety disorder (1 paper, 2025). An anxiety disorder characterized by excessive and difficult-to-control worry about a number of life situations. "Specifically, the ANKK1-DRD2 genes are linked to comorbid MDD and Generalized anxiety disorder (GAD) in adults with ADHD, whereas the NCAM1 and DRD2 genes independently contribute to the susceptibility to MDD in these patients." (PMID 40547117, 2025).
Guillain-Barre syndrome (1 paper, 2022). A spectrum of rare post-infectious neuropathies that usually occur in otherwise healthy patients. "The expression of NCAM-1 has been found dysregulated during the course of COVID-19 neuroinfection and a potential role in Guillain-Barre syndrome has been reported." (PMID 35458486, 2022).
Hernia (1 paper, 2025). "Moreover, both NCAM1 and LTBP1 were consistently expressed in all patient samples, providing evidence of their involvement in the hernia development." (PMID 39903526, 2025).
kidney damage (1 paper, 2021). "NCAM1 is downregulated during differentiation into kidney epithelial cells and re-activated in a specific subset of cells that undergo dedifferentiation to behave as highly stem/progenitor cells (e.g., in the regenerative response following kidney damage)." (PMID 34948246, 2021).
membranous nephropathy (1 paper, 2025). "Both EXT1/EXT2 and NCAM1 are associated with subepithelial immune deposits, suggesting mechanisms of injury in MLN that are different from other forms of membranous nephropathy." (PMID 41440943, 2025).
myelofibrosis (1 paper, 2024). A partial or complete replacement of the bone marrow stroma by fibrous tissue. "Murine ThPO and JAK2V617F myelofibrosis models showed co-expression of Nrp2 and Ncam1 in osteolineage cells, while fibrosis-promoting MSC only express Nrp2." (PMID 38792002, 2024). "Advanced myelofibrosis was characterized by stromal spindle-shaped cells expressing both NRP2 and NCAM1 in aggregates and diffusely within the bone marrow space resulting in progressive osteosclerosis with anastomosing spicules." (PMID 38792002, 2024). "Together, these findings suggest that Nrp2 and Ncam1 double-expressing cells represent rare MSC able to differentiate toward the fibrotic and the osteogenic trajectory driving myelofibrosis and osteosclerosis." (PMID 38792002, 2024). "In fact, NCAM1 and NRP2 protein expression correlated with the severity of myelofibrosis in our clinical cohort." (PMID 38792002, 2024). "During early myelofibrosis in PMF, NRP2 and NCAM1 expression was increased in the endosteal niche." (PMID 38792002, 2024).
neurotoxicity (1 paper, 2022). Toxicity that causes injury to the central or peripheral nervous system or damages its function. "The third module included 3 genes in Neurotoxicity (Itpr1, Trim8, Lrp1), 4 in Blood–brain barrier (Ptpn23, Claudin5, Plectin, Mmp2) and 4 in Cognitive function (Slc8a3, Srf, Nf1, Ncam1)." (PMID 35899365, 2022).
tauopathy (1 paper, 2025). Neurodegenerative disorders involving deposition of abnormal tau protein isoforms (tau proteins) in neurons and glial cells in the brain. "Our study demonstrates that targeting NCAM1 represents a promising strategy to mitigate tauopathy in AD." (PMID 40502793, 2025). "Finally, intracerebroventricular injection of NCAM1 antibody significantly alleviated pathological tau accumulation and glial inflammation in PS19 tauopathy mouse brains, which had previously been reported to exhibit increased level of 18:2 FFA." (PMID 40502793, 2025).
vitreous hemorrhage (1 paper, 2017). Blood extravasation in the vitreous humor. "The degree of vitreous hemorrhage was negatively correlated with NrCAM, NCAM-1 and DcR3 (R2 = 0.709, 0.669 and 0.563, respectively)." (PMID 29095861, 2017).